BDNF (brain derived neurotrophic factor)
Diseases named in the same sentence as BDNF in open-access papers (continued):
Sharing a sentence is not in itself a finding about the gene and the disease.
endometriosis (54 papers, 2011 to 2026). The growth of functional endometrial tissue in anatomic sites outside the uterine body. "Further studies are needed to be undertaken to investigate the role of BDNF in endometriosis pathophysiology and the diagnostic value of BDNF in endometriosis." (PMID 38218833, 2024). "BDNF is known to regulate both initiation and maintenance of chronic endometriosis-associated pain involving neuroangiogenesis and innervation in the pelvic organs." (PMID 38559689, 2024). "Other limitation for our study is number od included articles and participants, for considering BDNF as a diagnostic value for endometriosis, more studies should be included and determined." (PMID 38218833, 2024). "Recent studies have proposed a potential association between BDNF and endometriosis, highlighting BDNF as a promising candidate biomarker for this condition." (PMID 38218833, 2024). "The meta-analysis of the included studies revealed a significant association between BDNF levels and endometriosis." (PMID 38218833, 2024). "The aim of this systematic review and meta-analysis is to evaluate the existing evidence on the association between BDNF levels and endometriosis." (PMID 38218833, 2024). "Considerably more work will need to be done to determine the correlation between BDNF level and endometriosis and to evaluate the diagnostic value of BDNF." (PMID 38218833, 2024). "IL-1β can aggravate endometriosis-associated pain and inflammation by increasing the secretion of brain-derived neurotrophic factor in eutopic endometrial stromal cells at the mRNA and protein level." (PMID 37893241, 2023). "Brain-derived neurotrophic factor is associated with the proliferation of endometrial tissue and is considered a potential target for infertile patients with endometriosis." (PMID 35419445, 2022). "BDNF circulating levels were later associated with pelvic pain scores in another group of women with endometriosis compared with the relevant control group." (PMID 35300713, 2022). "Hidrox® treatment by reducing the persistent state of oxidative stress in the hippocampus of endometriosis animals was able to restore BDNF levels which would be a central mechanism underlying the pro-oxidative and behavioral changes in endometriosis." (PMID 34064310, 2021). "BDNF not only participates in endometriosis-associated inflammation but also promotes peripheral and central nervous systemic pain." (PMID 32145751, 2020). "Endometriosis-associated pain is related not only to the number and distribution of nerves but also to some neurotrophins, especially BDNF and NGF." (PMID 32145751, 2020). "Specific polymorphisms in the BDNF gene have been found to be associated with incidence of endometriosis-related infertility (p < 0.05)." (PMID 28701212, 2017). "NGF and BDNF have recently been described in the context of endometriosis associated pain and regulation of neurogenesis in and around the sites of lesions." (PMID 25207642, 2014). "However, the existing literature on the association between BDNF and endometriosis is still limited and characterized by inconsistencies in findings." (PMID 38218833, 2024). "Dyspareunia in patients with endometriosis may be associated with IL-8, IL-10, and BDNF, as these biomarkers contribute to inflammatory and neurogenic processes that heighten pain sensitivity." (PMID 39796020, 2024). "The significant increase in BDNF in endometriosis and the abnormal distribution of different types of nerve fibres may be the causes of endometriosis-associated pain." (PMID 35300713, 2022). "BDNF and TrKB are closely related to dysmenorrhoea caused by endometriosis and may be important in the pathobiology or pathophysiology of endometriosis." (PMID 35300713, 2022). "The present study demonstrated that BDNF and TrKB may be associated with endometriosis severity." (PMID 35300713, 2022).
endometriosis (continued). "BDNF, a member of the neurotrophin growth factors family, could promote oocyte maturation and embryo development and was also associated with infertility and endometriosis." (PMID 32564444, 2020). "Here we have found that gain of methylation at 3 ‘sequence of the BDNF gene is functionally linked to up-regulation of gene transcription and protein secretion by endometriotic stromal cells, suggesting a role for epigenetic gene regulation in the mechanisms of pain generation in endometriosis." (PMID 28125717, 2017). "Circulating levels of BDNF were shown to be significantly increased in women with endometriosis, potentially influencing several aspects of eating behavior." (PMID 41563503, 2026). "The highest BDNF levels were observed in patients with fibromyalgia, although elevated levels were observed across multiple pain conditions including endometriosis and knee osteoarthritis." (PMID 41084412, 2026). "Further studies on the relationship between BDNF methylation levels and pain symptoms in endometriosis patients will help reveal the molecular mechanisms of endometriosis-related pain." (PMID 40004233, 2025). "BDNF levels were found to be significantly higher in patients with endometriosis, particularly in early stages (I–II), where BDNF was the only biomarker independently differentiating cases from controls." (PMID 41009445, 2025). "In endometriosis (EMs), Brain-Derived Neurotrophic Factor (BDNF) plays a significant role in the disease’s development and associated symptoms." (PMID 41009445, 2025). "The mean BDNF serum concentrations in endometriosis and healthy patients were 21.66 ng/mL (SD 6.02) and 19.06 ng/mL (SD 4.81), respectively." (PMID 39062909, 2024). "The result of the sensitive analysis showed a significant increase in BDNF levels in both plasma and serum in endometriosis." (PMID 38218833, 2024). "Capillary blood vessels formed around endometriosis tissue would help this increased amount of BDNF reach the peripheral circulation." (PMID 38218833, 2024). "This study aims to investigate the possible relationship between sexual quality of life in patients affected by endometriosis and a series of biomarkers: interleukin 8 (IL-8), interleukin 10 (IL-10), and Brain-Derived Neurotrophic Factor (BDNF)." (PMID 39796020, 2024). "As well, there are multiple other factors to be involved, including other cells in the endometriosis microenvironment (e.g., mast cells) and other neuroproliferative factors (e.g., BDNF and Trk receptors) that can confound these correlations." (PMID 38785989, 2024). "Although BDNF was significantly higher in endometriosis compared with healthy controls, no significant changes were reported between different stages of endometriosis." (PMID 38218833, 2024). "Regarding pain, statistically significant correlations were found with tissue levels of IL-8, tissue levels of BDNF, endometriosis severity, and history of surgical interventions." (PMID 39796020, 2024). "BDNF’s involvement in nerve sensitization and pain underscores its importance in diagnosing pain-related symptoms of endometriosis and developing targeted pain management treatments." (PMID 39202309, 2024). "The primary objective of this study was to investigate the role of IL-8, IL-10, VEGF-A, and BDNF in assessing and determining endometriosis severity." (PMID 39202309, 2024). "This study revealed a significant difference between patients diagnosed with endometriosis and healthy control in the level of BDNF." (PMID 38218833, 2024). "The search strategy included relevant keywords and medical subject headings (MeSH) terms related to BDNF, endometriosis, and protein levels." (PMID 38218833, 2024). "The results showed that blood levels of BDNF are significantly higher in endometriosis patients (SMD: 1.13 95% CI 0.54 to 1.73, p = 0.0002; I2 = 93%)." (PMID 38218833, 2024).
endometriosis (continued). "This systematic review and meta-analysis aim to synthesize the available evidence and evaluate the possible relationship between BDNF protein levels and endometriosis." (PMID 38218833, 2024). "Sexual satisfaction is negatively influenced by tissue levels of IL-8, both serum and tissue levels of BDNF, endometriosis severity, and history of surgical interventions." (PMID 39796020, 2024). "The result of the present systematic review and meta-analysis indicates that BDNF levels significantly increase in patients diagnosed with endometriosis compared to healthy controls." (PMID 38218833, 2024). "In conclusion, our study revealed that BDNF level is significantly higher in patients with endometriosis compared to healthy control." (PMID 38218833, 2024). "Elevated levels of BDNF have been reported in the peritoneal fluid, serum, and endometrial tissue of women with endometriosis compared to healthy controls." (PMID 38218833, 2024). "The pooled standardized mean difference (SMD) of BDNF levels between women with endometriosis and controls was 0.87 (95% confidence interval [CI] 0.34 to 1.39, p = 0.001; I2 = 93%)." (PMID 38218833, 2024). "Further investigation and experimentation into the correlation between BDNF and endometriosis is strongly recommended." (PMID 38218833, 2024). "For the comparison of the control group with low-stage disease, only BDNF was retained, meaning that only BDNF was independently informative as a predictor of low-stage endometriosis." (PMID 37509088, 2023). "The validation study (study 2) aimed to establish the clinical performance of the developed endometriosis IVD test, combining an ELISA kit to measure serum concentrations of BDNF and CA125 and a diagnostic software hosting the diagnostic algorithm." (PMID 37509088, 2023). "Both studied biomarkers, CA125 and BDNF, can distinguish endometriosis cases from controls with statistical significance." (PMID 37509088, 2023). "Combined, CA125 and BDNF can distinguish controls from endometriosis cases with more accuracy than each biomarker independently, with the former performing very well in the high-stage group and the latter performing better in the low-stage group." (PMID 37509088, 2023). "Several research groups have demonstrated that BDNF appears to be a reliable biomarker for early stages (I–II) of endometriosis." (PMID 37509088, 2023). "Brain‐derived neurotrophic factor (BDNF) and its receptors, tropomyosin‐related kinase B (TrkB) and P75 was found to be more highly expressed in tissues with intestinal endometriosis lesions than in other types of endometriosis." (PMID 37632165, 2023). "In order to further explore the effects of BDNF in the proliferation of ESCs and endometriosis, we transfected BDNF overexpression plasmid to shTim-3 ESCs and gave Tim-3 inhibitor and K252a to the rats’ endometriosis model." (PMID 38114892, 2023). "In summary, our study shows that TIM-3 is involved in the proliferation of endometriosis cells by BDNF-mediated PI3K/AKT axis." (PMID 38114892, 2023). "This confirms what was previously found by other research groups: BDNF concentrations are higher in endometriosis patients than in controls in plasma and serum." (PMID 37509088, 2023). "Another biomarker of interest, brain-derived neurotrophic factor (BDNF), has been linked to several pathways disrupted in women with endometriosis." (PMID 37509088, 2023). "In patients with stage II endometriosis, the expression of BDNF in the ectopic endometrium was significantly higher than that in the eutopic endometrium (P < 0.05)." (PMID 35300713, 2022). "Increased serum BDNF concentrations have been observed in patients with endometriosis with central sensitivity syndrome." (PMID 35300713, 2022). "A recent study demonstrated that the level of BDNF in circulation is found to be elevated in women with endometriosis compared to healthy controls, and it decreased after the surgical removal of lesions." (PMID 35334511, 2022).
endometriosis (continued). "Ding and colleagues went on to confirm the role of BDNF in endometriosis and pelvic pain in their observation of higher BDNF levels in the peritoneal fluid of women with endometriosis and pelvic pain compared to the control group." (PMID 35300713, 2022). "Pain is a typical symptom of endometriosis, so the conduction pathways were analyzed and the brain-derived neurotrophic factor (BDNF) was found to be elevated in women with endometriosis compared to the control group." (PMID 34638893, 2021). "According to the results, significant increases of DRG‐NGF and BDNF were observed in the endometriosis group compared to the other groups in phase one." (PMID 34806344, 2021). "Both serum and peritoneal fluid BDNF concentrations were also significantly lower in the endometriosis group compared to control and RJ groups (p < 0.05)." (PMID 34806344, 2021). "Furthermore, the relationship between BDNF secretion and the effect of melatonin is further validated in earlier studies of conditions that concur with excessive activation of the stress system associated with inflammation such as in fibromyalgia and endometriosis." (PMID 32302347, 2020). "Brain Derived Neurotrophic Factor (BDNF) has been identified as a potential peripheral early diagnostic marker, as its mean plasma concentrations were twice as high in endometriosis cases in contrast to asymptomatic or healthy controls." (PMID 32575462, 2020). "The expression of several molecules with neurotrophic effects, including the nerve growth factor, neurotrophin-3 and the brain-derived neurotrophic factor, has been reported in women with endometriosis." (PMID 31491902, 2019). "They confirmed that the expression of NGF and NT-3 were increased significantly in the peritoneal fluid (PF) of patients with endometriosis, and BDNF was also detected in PF of women with peritoneal endometriotic lesion." (PMID 28288663, 2017). "BDNF mRNA expression has previously been shown in eutopic endometrium of women with endometriosis and also in normal human and mammalian uterus as well as endometrium (glandular epithelium and stroma)." (PMID 27519317, 2016). "We confirm, for the first time in histological sections, that BDNF is present in endometriosis lesions, both DIE and in peritoneal lesions." (PMID 27519317, 2016). "No studies have evaluated the presence and location of BDNF in endometriosis lesions, although BDNF is present in eutopic endometrium from women with endometriosis." (PMID 27519317, 2016). "There are also changes in BDNF levels in patients with endometriosis." (PMID 40004233, 2025). "Additionally, in our sensitive analysis, we have compared BDNF levels in serum and plasma separately, which can lead to a better vision for utilizing the BDNF as a novel biomarker for endometriosis." (PMID 38218833, 2024). "The results indicate that women with endometriosis have higher levels of BDNF." (PMID 38218833, 2024). "The pooled standardized mean difference (SMD) of BDNF levels between women with endometriosis and controls was 0.87 (95% confidence interval [CI] 0.34 to 1.39, p = 0.001; I2 = 93%), indicating higher BDNF levels in women with endometriosis compared to controls." (PMID 38218833, 2024). "Therefore, a comprehensive evaluation of the available evidence is warranted to clarify the role of BDNF in endometriosis." (PMID 38218833, 2024). "Since BDNF increases in both serum and plasma, it can be utilized as an accessible, fast, non-invasive, and inexpensive method for not only diagnosis but also evaluating the severity and treatment respond in women with endometriosis." (PMID 38218833, 2024). "However, BDNF expression in eutopic endometrium is positively correlated with stages of endometriosis." (PMID 38218833, 2024). "BDNF is another neurotrophin that is increased in patients with endometriosis." (PMID 37893241, 2023).
endometriosis (continued). "Here, two studies aimed to develop a diagnostic tool that could identify all stages of endometriosis by combining CA125, BDNF and clinical variables." (PMID 37509088, 2023). "BDNF is mainly secreted by macrophages and is regulated by oestrogen in endometriosis lesions." (PMID 37632165, 2023). "TIM-3 can promote the proliferation of endometriosis by BDNF-mediated PI3K/AKT axis in vivo and in vitro, which may provide a new therapeutic target for the treatment of endometriosis." (PMID 38114892, 2023). "However, this study is limited to the assessment of a single time point in the course of a woman’s endometriosis journey, and the important role of BDNF and TrKB in promoting the mechanism of endometriosis remains to be further studied." (PMID 35300713, 2022). "This study further validated the effect of the BDNF/TrKB signalling pathway on the process of endometriosis and analysed changes in the expression of these factors, together with associated changes in the degree of dysmenorrhoea, in different parts of the endometrium at different stages." (PMID 35300713, 2022). "This suggests that BDNF and TrKB may be important in the pathobiology or pathophysiology of endometriosis." (PMID 35300713, 2022). "Induction of endometriosis leads to hyperalgesia, which may be associated with a significant increase in NGF, BDNF, and CGRP levels in DRG." (PMID 34806344, 2021). "In addition, immunohistochemistry revealed the in situ colocalization of macrophages, BDNF, and nerve fibers in endometriosis lesions." (PMID 32145751, 2020). "The main objective of this immunohistochemistry study was to assess for the presence and localization of the neurotrophins NGF and BDNF and their receptors, TrkA and, TrkB and p75, in endometriosis lesions and to compare these between PE and DIE by using quantitative methods." (PMID 27519317, 2016). "Moreover, increased expression of BDNF and neurotrophin 4/5 has been demonstrated in the endometrium of women with endometriosis versus healthy controls." (PMID 26064879, 2015). "This multifaceted mechanism of melatonin’s effect on pain also results in a reduction in serum BDNF, an effect observed in this study, which corroborates the results of a previous randomized clinical trial concerning chronic pelvic pain induced by endometriosis." (PMID 25052847, 2014). "In addition, melatonin reduced the BDNF serum level in patients with chronic pelvic pain induced by endometriosis." (PMID 25052847, 2014). "Brain-derived neurotrophic factor (BDNF) levels are low in the follicular fluid of women with endometriosis and suggest that neurotrophins may contribute to the pathogenesis via aberrant oxidative stress mechanisms." (PMID 22203846, 2011). "Therefore, BDNF, although ineffective as a marker for excluding the disease, may be a valuable element of non-invasive diagnostics supporting the early diagnosis of endometriosis." (PMID 41009445, 2025). "Although BDNF is primarily synthesized in the brain, elevated levels of BDNF have been detected in the plasma, peritoneal fluid, and endometrial tissue of women with endometriosis compared to healthy controls, sustained by the local interaction of inflammatory factors and estrogen." (PMID 40075795, 2025). "However, in backwards stepwise regression analysis based on AIC, for the comparisons of the control group with all cases and with the high-stage disease cases, both CA125 and BDNF were retained, meaning they were both independently informative as predictors of endometriosis." (PMID 37509088, 2023). "A previous study found that BDNF (Met) single-nucleotide polymorphism, an IRG, was associated with endometriosis-related infertility women, suggesting that low levels of BDNF may be responsible for poor in vitro fertilization (IVF) outcomes in infertile patients with the BDNF (Met/Met) genotype." (PMID 36660246, 2023).